PDGFRA (platelet derived growth factor receptor alpha)
Diseases named in the same sentence as PDGFRA in open-access papers (continued):
Sharing a sentence is not in itself a finding about the gene and the disease.
glioma (continued). "PDGFRA is also mutated or overexpressed in a large proportion of H3.3-G34R/V mutant gliomas and is commonly utilized in the generation of H3.3-G34R/V mutant glioma models." (PMID 37509641, 2023). "G34-DHG is a new high-grade glioma with high frequency of PDGFRA and MUC gene family mutations." (PMID 35109850, 2022). "GISTIC 2.0 analysis revealed that in gliomas with high-risk scores, the amplification mainly occurred in chromosomal regions 1q32.1, 3q26.33, 4q12, 7p11.2, and 12q14.1, where several key oncogenes (PDGFRA, EGFR, MDM2, SOX2, and CDK4) were located." (PMID 35116021, 2021). "PDGFRA is an especially attractive driver mutation as it is expressed in neural stem cells and known to be critical to gliomagenesis; however, it remains to be determined how it exactly exerts its effects in the development of glioma." (PMID 31788444, 2019). "Using sequencing data from Project GENIE, which contains 453 PDGFRA missense mutations from over 18,000 samples across 37 tumor types, we discovered that over 50% of PDGFRA missense mutations were located in the extracellular domain in glioma and colorectal cancer." (PMID 30389923, 2018). "Indeed, the Proneural group was found to have two subclasses: those tumors tightly associated with IDH mutations and the glioma-CpG island methylator phenotype (G-CIMP) that is mutually exclusive with those harboring PDGFRA alterations." (PMID 29312129, 2017). "Increased PDGFRA signaling is an essential pathogenic factor in many subtypes of gliomas." (PMID 24489888, 2014). "However, compared to the established close association between EGFR high expression and EGFR gene amplification and mutation, the regulation mechanism for PDGFRA expression in glioma cells is yet unclear." (PMID 23630597, 2013). "Interestingly, in both the GSE16011 and the Rembrandt data sets, PDGFRA-high gliomas were associated with younger age at disease onset compared to PDGFRA-low gliomas (p<0.01, t test)." (PMID 23630597, 2013). "Furthermore, compared to PDGFRA-low and PDGFRA-intermediate gliomas, PDGFRA-high gliomas were associated with significantly higher frequency of loss of heterozygosity (LOH) at 1p and 19q." (PMID 23630597, 2013). "PDGFRA gene amplification may be the underlying genetic mechanism driving PDGFRA overexpression in gliomas." (PMID 19707201, 2009). "For instance, PDGFRA (Platelet-Derived Growth Factor Receptor Alpha) has been implicated in the promotion of cell proliferation in peripheral T-cell lymphoma and is negatively regulated in gliomas through an ERK-dependent mechanism that reduces cell proliferation." (PMID 39456519, 2024). "A recent study outlined a novel mechanism involved in the pathogenesis of IDH-mutant gliomas: methylation of insulator protein binding sites within DNA, leading to aberrant contact of the PDGFRA promoter with distant enhancer elements, causing overexpression of PDGFRA, a known glioma oncogene." (PMID 27556016, 2016). "Our mouse glioma model provides a unique entry point for studying the propensity of glioblastoma to amplify RTKs, as our model is genetically defined with only two initiating mutations–a point mutant of PDGFRα with elevated kinase activity and loss of INK4A/Arf." (PMID 25683249, 2015). "However, the molecular alterations underlying glioma patients’ response to PDGFRA antagonists are unknown." (PMID 19707201, 2009). "Thus, the aim of this study was to define the frequency of PDGFRA and PDGFA expression in a large series of gliomas and to determine whether expression of PDGFRA is driven by PDGFRA gene mutations and/ or amplification." (PMID 19707201, 2009).
glioma (continued). "The combination of avapritinib and venetoclax, co-targeting the oncogenic signal and its transcriptional regulator, presents a translatable dual-targeting strategy to improve outcomes in PDGFRA-driven glioma." (PMID 42157323, 2026). "This positions PDGFRA-targeted vaccines as a significant innovation on the horizon for glioma immunotherapy." (PMID 41847712, 2026). "Understanding how PDGFRA shapes this immunosuppressive landscape is paramount for developing effective immunotherapies, especially given the minimal response rates of gliomas to conventional checkpoint inhibitors." (PMID 41847712, 2026). "Immunoblotting of GSC cell fractions confirmed that PDGFB localized to the chromatin fraction, demonstrating that exogenous PDGFB can localize to the nucleus and bind chromatin in glioma cells bearing the cognate receptor, PDGFRA." (PMID 40060572, 2025). "This phase II clinical trial evaluated the safety and efficacy of nilotinib in patients with recurrent, platelet-derived growth factor receptor alpha (PDGFRA)-enriched high-grade gliomas." (PMID 40709015, 2025). "In adult-type high-grade glioma, tumors with PDGFRA amplification and EGFR amplification demonstrate significantly elevated perfusion parameters, such as rCBV and relative cerebral blood flow." (PMID 40853542, 2025). "Subsequently, the drug was used in 8 pediatric and young adult patients with PDGFRA-altered diffuse midline glioma (DMG) or other high-grade glioma." (PMID 40094009, 2025). "Avapritinib demonstrates CNS penetrance in preclinical models with steady-state brain-to-plasma ratios ranging 0.74–1.0032, and exhibits clinical activity in PDGFRA-altered high-grade glioma patients." (PMID 40819143, 2025). "Alterations identified by Titan-CNA in the 4q12 MCR covered recognized oncogenes and genes with known biological significance in glioma and glioblastoma, including PDGFRA, REST, and CLOCK9,23,24." (PMID 40319462, 2025). "For example, PDGFRA-targeted therapies, such as avapritinib, have shown efficacy in models with PDGFRA amplification (NCT04773782), while hemispheric gliomas harboring the G34R mutation, along with the PDGFRA C235Y variant, respond to infigratinib." (PMID 40647519, 2025). "CircCDK14 increases PDGFRA expression by sponging miR‐3938 to promote invasion and reduce sensitivity to ferroptosis in glioma." (PMID 40356340, 2025). "Research demonstrates that PDGFRα signaling is crucial for glioma-like hyperplasia and the preservation of glioma stem cell characteristics via pathways such as PDGFRα/STAT3/RB1." (PMID 40332008, 2025). "lncRNA LINC02283 is co-amplified with the PDGFRA locus and highly expressed in PDGFRA-driven high-grade gliomas, enhancing GBM malignancy by modulating PDGFRA and its downstream signaling pathways." (PMID 40565099, 2025). "In adult patients, glioma tumors with a PDGFRA amplification frequently harbor a genomic deletion of exons 8 and 9, which encode part of D4 and D530." (PMID 38532028, 2024). "By sponging miR-3938, it upregulates the oncogenic gene PDGFRA and thus reduces glioma cells' sensitivity to ferroptosis." (PMID 39309434, 2024). "This suggests that the PDGFRα or PDGFRβ pathway plays a role in cancer cell proliferation during the various stages of glioma development." (PMID 38473403, 2024).
glioma (continued). "Another key element in gliomas is the amplification of the platelet-derived growth factor receptor alpha (PDGFRα), which primarily activates the Ras/Raf/MAPK pathway." (PMID 39770078, 2024). "Another study assessed OS in recurrent pediatric gliomas with this combination in six cases with confirmed PDGFRA-driven gliomas." (PMID 39202398, 2024). "Platelet derived growth factor receptor α (PDGFRα) facilitated the malignant biological behavior of glioma by promoting protein kinase A-dependent serine phosphorylation of DOCK1." (PMID 38438882, 2024). "We previously identified reciprocally expressed gene modules consistently co-expressed with EGFR or PDGFRA (named EM or PM, respectively) in glioma transcriptome." (PMID 37055795, 2023). "For example, an obvious phUMR was observed at the promoter of PDGFRA, a well-known prominent glioma oncogene." (PMID 37118755, 2023). "Where PDGFRA genes are unaltered, proneural gliomas almost always have increased activity of the genes PIK3CA or PIK3R1." (PMID 37345193, 2023). "Glioma cells express PDGFRA, while PDGFRB is predominantly localized in the glioma-associated extracellular matrix." (PMID 37700840, 2023). "As observed in clinical data of IDH1-mut AML patients, IDH1-mut glioma patients with high PDGFRA expression also showed significantly worse survival rates, supporting a strong clinical relevance of this mechanism." (PMID 36411356, 2023). "It has been found that circCDK14 sponges miR-3938 and upregulates PDGFRA expression, resulting in resistance to ferroptosis and promotion of glioma progression." (PMID 37332354, 2023). "Our finding of upregulated PDGFRA expression in connection with altered DNA looping in IDH1-mut AML now extends this mechanism of action beyond the context of glioma." (PMID 36411356, 2023). "Overexpression of PDGFRA has been shown to be a common driver of tumorigenesis in humans and dogs with gliomas, and to be present more frequently in high‐grade gliomas." (PMID 37246729, 2023). "Glioma cells meeting the proneural signature most commonly had IDH1/2 mutations, as well as focal amplification of RTK receptor gene PDGFRA." (PMID 37345193, 2023). "A subgroup of glioma carry genetic 4q12 amplification including platelet derived growth factor receptor α (PDGFRA) and insulin like growth factor binding protein 7 (IGFBP7)." (PMID 36043552, 2023). "More recently, it was reported that OLIG2 modulates growth factor signaling in two distinct populations of glioma stem-like cells depending on their EGFR or PDGFRα expression." (PMID 37511403, 2023). "Mutations including IDH1, PDGFRA, ATRX, etc. have been identified to be associated with glioma tumorigenesis, tumor development and patients’ prognosis." (PMID 36720864, 2023). "Like KDR, those PDGFRA co‐amplified genes are suspected driver genes to promote the progression of glioma." (PMID 36043552, 2023). "CircCDK14 can reduce the sensitivity of glioma cells to ferroptosis by regulating PDGFRA expression, thereby promoting the formation and metastasis of gliomas in vivo." (PMID 37168995, 2023). "Both PDGFRA and KIT are notable driver mutations of glioma, and were observed to be associated with poor prognosis in our cohort and TCGA glioma cohort." (PMID 36720864, 2023). "GRB14 plays glioma-promoting roles through PDGFRα, which promotes glioma progression and treatment resistance." (PMID 37955724, 2023). "The GISTIC 2.0 assessment uncovered numerous remarkable amplified regions containing multiple oncogenes in glioma patients with higher risk scores, consisting of 1q32.1 (PIK3C2B), 12q14·1(CDK4), 7p11·2 (EGFR), and 4q12 (PDGFRA)." (PMID 36311792, 2022).
glioma (continued). "Our findings indicated that circCDK14 behaves like a ceRNA to accelerate glioma progression via the miR-3938/PDGFRA axis." (PMID 35002529, 2022). "Previous research revealed that THZ1 treatment induces EGFR and PDGFRa expression and multiple downstream oncogenic signalling pathways in glioma." (PMID 36076237, 2022). "Proneural glioma are defined by the expression of the neurogenesis markers PDGFRA, NKX2-2, and OLIG2, and they are IDH1 mutants." (PMID 35328529, 2022). "DER enhancer‐associated genes, including PDGFRA and NFIA, have been linked to the tumourigenicity of glioma models and/or neural progenitor cell fate decisions." (PMID 34767259, 2022). "Other authors also reported concomitant expressions of A2B5, O4 and PDGFRα in a series of 25 gliomas of various types and grades." (PMID 35563061, 2022). "Upon further evaluation, we demonstrated that circCDK14 accelerated glioma progression and inhibited glioma cells' sensitivity to Fp via regulating the miR-3938/PDGFRA axis." (PMID 35002529, 2022). "It was reported that circCDK14 promotes tumor progression and resists ferroptosis in glioma by regulating PDGFRA." (PMID 36266731, 2022). "We revealed for the first time the biological activity of circCDK14 in glioma, suggesting that the circCDK14/PDGFRA axis is an excellent candidate for targeted anti-glioma therapy." (PMID 35002529, 2022). "In conclusion, circCDK14 induces tumor in glioma and increases malignant tumor behavior via the miR-3938/PDGFRA axis." (PMID 35002529, 2022). "This further leads to the ectopic interaction of the IDH enhancer with PDGFRA (platelet-derived growth factor receptor alpha), leading to its constitutive expression and the development of gliomas." (PMID 36589746, 2022). "Then, qRT-PCR and Western blot were employed for the detection of mRNA and protein expression of PDGFRA while overexpression or knockdown of circCDK14 in glioma cells." (PMID 35002529, 2022). "In addition to the link identified between CD73 and EGFR-amplified AC-like adult glioblastoma, scRNA-seq showed that CD73 expression may be independently associated with OPC-like high-grade gliomas in pediatric patients, some of whose tumors also exhibit elevated PDGFRA expression." (PMID 35973991, 2022). "In a glioma subset with histone H3 mutation (H3K27M DMGs), PDGFRA amplification and mutation were reported together with histone H3.3 mutation." (PMID 35109850, 2022). "PDGFRA is known to participate in gliomagenesis by transducing multiple downstream proliferative signals, and seems to also be involved in glioma invasion into dense white-matter fibers, as confirmed by studies on diffuse intrinsic pontine gliomas." (PMID 35626112, 2022). "As discussed, our group showed that the combination of PDGFRA inhibitor dasatinib with mTOR inhibitor everolimus significantly improved the survival of pediatric high-grade glioma than either treatment alone." (PMID 35978801, 2022). "GD3 formed a complex with PDGFRα and activated kinase Yes in lipid rafts, thus promoting proliferation, invasion, and a malignant phenotype of human glioma cells." (PMID 34064863, 2021). "Aberrant expression of PDGFRα has been identified in multiple types of human cancers, including medulloblastomas, papillary thyroid cancer, colorectal cancer, gliomas, liver cancer, and ovarian cancer." (PMID 33568640, 2021).
glioma (continued). "miR-34 can inhibit the growth of glioma cells by targeting the expression of oncogenes such as Notch-1, Notch-2, c-Met, and platelet-derived growth factor receptor alpha (PDGFRA)." (PMID 34540663, 2021). "In animal model studies, PDGFA activates the PDGFRA-positive neural stem cell proliferation in the subventricular zone, which differentiates and develops lesions similar to glioma." (PMID 34199460, 2021). "PDGFRA signaling, on the other hand, is frequently elevated in adult and pediatric gliomas, including the rare and universally fatal diffuse midline glioma (DMG), which is predominantly found in pediatric patients." (PMID 34480532, 2021). "GBM tumor subtyping is based on gene amplification of actionable key glioma drivers (50% EGFR amplification in classical or 10–15% PDGFRA amplification in proneural subtypes)." (PMID 34830952, 2021). "For example, platelet-derived growth factor receptor α (PDGFRα) stimulates the growth of gliomas and several other cancer types." (PMID 33922595, 2021). "The frequency of PDGFRA amplification in lower-grade glioma has only been reported from studies of small numbers of low-grade gliomas, and the evidence was insufficient to reach conclusions about the prognostic value." (PMID 34257410, 2021). "Targeting the PDGFRA with a neutralizing human monoclonal antibody inhibits the growth of tumor xenografts, but, notably, there is more preclinical evidence linking PDGFR-β to glioma proliferation and survival than PDGFRA." (PMID 34830952, 2021). "In tumor cells, PDGFRA and PDGFA are commonly found and PDGFB and PDGFRB are expressed in glioma-linked endothelial cells." (PMID 34199460, 2021). "In the PDGFRA#4 case, MET overexpression was most likely caused by the presence of a PTPRZ1-MET fusion, as PTPRZ1 is among the highest expressed genes in glioma, and the fusion places MET under the control of the PTPRZ1 promoter." (PMID 34572759, 2021). "The proportion of CD8 T-cells, another prominent immune cell type in high-grade gliomas, was associated with oncogene amplifications in MYCN, PDGFRA, and MDM2." (PMID 34496929, 2021). "GISTIC 2.0 analysis identified several significant regions of amplification harboring multiple oncogenes in gliomas with a high-risk score, including 1q32.1 (PIK3C2B), 4q12 (PDGFRA), 7p11·2 (EGFR), and 12q14·1(CDK4)." (PMID 32023222, 2020). "Mechanistic investigations revealed that CHSY1 selectively regulates PDGFRA activation and PDGF-induced signaling in glioma cells by stabilizing PDGFRA protein levels." (PMID 32019907, 2020). "Crenolanib, a PDGFR inhibitor in Phase II trials for glioblastoma with PDGFRA gene amplification, inhibits glioma cells." (PMID 32019907, 2020). "Two activating PDGFRA gene rearrangements in gliomas have been identified and suggest the possibility that these PDGFRA mutants behave as oncogenes." (PMID 33081688, 2020). "Other alterations we observed that would be expected to cooperate with PI3K activation included AKT2 and PDGFRA over-expression, both also frequent aberrations observed in glioma." (PMID 33053751, 2020). "In this study, we showed that CHSY1 is not only a prognostic factor for poor survival of glioma patients but that it also activates the PDGFRA pathway to promote tumorigenesis." (PMID 32019907, 2020). "Pair-wise comparison of CNAs in the glioma-associated genes ALK, PDGFRA, VEGFR2/KDR, EGFR, MET and FGFR1 was performed employing MLPA techniques." (PMID 30894200, 2019). "Ten patients with PDGFRa overexpression and two patients with PDGFRb had a high-grade glioma, including GBM, anaplastic oligoastrocytoma, anaplastic oligodendroglioma and anaplastic pleomorphic xanthoastrocytoma (PXA)." (PMID 31882734, 2019).